DAPK1 (death associated protein kinase 1)
Diseases named in the same sentence as DAPK1 in open-access papers (continued):
Sharing a sentence is not in itself a finding about the gene and the disease.
tumor (continued). "Collectively, these analyses suggested that loss of DAPK1 in HCT116 cells affected transcripts involved in enhancing tumor–stroma binding and mesenchymal transition." (PMID 31772156, 2019). "Concerning pathological features, tumor differentiation was significantly associated with the DAPK1 SNVs rs11141901 (p-value = 0.041) and rs1041326 (p-value = 0.005)." (PMID 31528229, 2019). "DAPK1 has been shown to be inactivated by Netrin-158 to potentiate tumor-associated vessel formation in metastatic lung cancer." (PMID 31772156, 2019). "In a wide variety of tumors, DAPK1 expression is frequently suppressed and the tumor-suppressive function of DAPK1 is linked to its role in cell death via apoptosis and autophagy." (PMID 30287790, 2018). "The phosphorylation on Ser71 by DAPK1 (Death-associated protein kinase 1), a known tumor suppressor, inhibited Pin1 catalytic activity during the cell cycle progression." (PMID 30096758, 2018). "It has been shown that cisplatin as well as 5-azacytidine touch off cytotoxic and growth inhibitory effects in vitro by demethylating the promoters of ESR1, BRCA1, RASSF1A, MLH1, MYOD1, hTERT, and DAPK1 to reexpress these tumor-associated genes." (PMID 29850477, 2018). "Epigenetic silencing of DAPK1 has been demonstrated to correlate with higher risk for recurrence and metastasis in various tumor entities." (PMID 28231808, 2017). "The death-associated protein kinase 1 (DAPK1) can act as an oncogene or a tumor suppressor gene depending on the cellular context as well as external stimuli." (PMID 28740751, 2017). "DAPK1 was a positive mediator of apoptosis which executed juncture of cell death signaling, and its loss or inactivation has been linked to human tumor." (PMID 28977860, 2017). "Death-associated protein kinase 1 (DAPK1), a Ca2+/calmodulin (CaM)-dependent serine/threonine protein kinase, plays important roles in diverse apoptosis pathways not only in tumor suppression but also in neuronal cell death." (PMID 27447806, 2017). "Death-Associated Protein Kinase 1 (DAPK1) belongs to a family of five serine/threonine (Ser/Thr) kinases that possess tumor suppressive function and also mediate a wide range of cellular processes, including apoptosis and autophagy." (PMID 27445685, 2016). "A significant strong association between DAPK1 promoter methylation and CC was shown and confirmed independently by histological tumor type, method used to evaluate methylation and source of control samples." (PMID 26267895, 2015). "Node-negative tumours also exhibited increased methylation levels of chemokine ligand 12 gene (CXCL12) and death-associated protein kinase 1 gene (DAPK1) compared with node-positive tumours." (PMID 25052224, 2014). "This single nucleotide variation resulted in allele-specific expression of DAPK1 in germline, non-tumor tissue (skin-derived fibroblasts)." (PMID 23383130, 2013). "We observed a positive correlation of miR-328 expression with a series of tumor suppressors which mediate cell cycle arrest, including death-associated protein kinase 1 (DAPK1)." (PMID 23077581, 2012). "Death-associated protein kinase-1 was found to be methylated in 35% (13 out of 37) of the pT1, 33% (seven out of 21) of the pT2, and 32% (seven out of 22) of the ⩾pT3 tumours." (PMID 17133271, 2006). "DAPK1 might also regulate macrophage polarization into TAMs, which are associated with tumor growth, invasion, and metastasis." (PMID 39926603, 2024). "Furthermore, we explored immune infiltration patterns between high and low DAPK1+ macrophage risk score groups, revealing distinct immune cell compositions and interactions within the tumor microenvironment." (PMID 39926603, 2024). "Tumor purity was lower in high DAPK1+ Macrophage risk score groups." (PMID 39926603, 2024).
tumor (continued). "Therefore, in our research, we comprehensively evaluated and validated an anoikis-related signature (including AKT2 and DAPK1), which was associated with tumor immune microenvironment and sensitivity to immunotherapy/ chemotherapy." (PMID 38310291, 2024). "Moreover, several studies indicate that DAPK1 is involved in tumor invasion and metastasis, as the loss of DAPK1 enhanced tumor budding and increased the invasion capacity." (PMID 35321516, 2022). "In addition, the apoptosis pathway mediated by death-associated protein kinase 1 (DAPK1)-TMS1 promotes tumor cell apoptosis." (PMID 37077808, 2022). "Nevertheless, we could verify an uPAR dysregulation upon DAPK1 loss in these FFPE CAM tumor slices, as suggested by our proteomic analysis." (PMID 35625969, 2022). "This supports the hypothesis that the loss of DAPK1 in HCT116 cells increases the ECM remodeling potential of this already aggressive tumor cell line." (PMID 35625969, 2022). "Interestingly, the promoter methylation of DAPK1 is known to be associated with aggressive and metastatic phenotype in many tumor types." (PMID 33718129, 2021). "If increased expression is associated with aggressive tumours, then, targeting DAPK1 could be a treatment method as well for curtailing tumour aggression and progression." (PMID 32566040, 2020). "Our observation that DAPK1-deficiency increases necroptosis may seem incompatible with DAPK1’s tumor-suppressing role." (PMID 32366830, 2020). "In addition to its role in cell death, DAPK1 has been implicated in the cell cycle, tumorigenesis, tumor metastasis, inflammation, oxidative stress and neurodegeneration." (PMID 31248062, 2019). "Next, we used the CAM assay to examine the role of DAPK1 loss for tumor growth." (PMID 31772156, 2019). "Recently we have reported that the loss of anti-migratory function of DAPK1 could be one of the reasons for tumor cell dissemination." (PMID 31772156, 2019). "This might also explain the better and faster adaptation of DAPK1 loss tumor cells in the physiological environment of PCTS experiment." (PMID 31772156, 2019). "Moreover, it was shown that DAPK1 was capable of suppressing oncogenic transformation caused by c-Myc and E2F, which blocks the tumor metastasis." (PMID 30287790, 2018). "However, among cases of gastrointestinal cancer, the association between DAPK1 methylation and tumor (T) stage, N stage, distant metastasis (M) stage, and cancer differentiation were not statistically significant." (PMID 28934284, 2017). "Promoter CpG islands methylation is one type of DNA methylation that could result in the inactivation of tumor suppressor genes, such as death-associated protein kinase 1 (DAPK1)." (PMID 28934284, 2017). "Death-Associated Protein Kinase 1 (DAPK1) is a member of the serine/threonine kinases that could act as a tumor suppressor in relation to its function to regulate apoptosis and autophagy." (PMID 28388658, 2017). "Thereby, it was suggested that EGCG may serve as a potential epigenetic modifier by altering the methylation status of genes encoding retinoic acid receptor beta (RARβ), cadherin 1 (CDH1), and death-associated protein kinase 1 (DAPK1) tumor suppressors to reactivate their expression." (PMID 37446908, 2023).
tumor (continued). "Similarly, DAPK1’s ability to regulate autophagy at different stages and its frequent epigenetic loss in tumor may be connected." (PMID 27445685, 2016). "Under the DNA methylation and gene silencing, Hypermethylation of tumour suppressor genes such as DAPK1, LRPPRC, and ZNF471 were reported." (PMID 41487403, 2026). "Apoptosis-related genes, including DAPK1 and p73 (Tumor protein 73), are inactivated through hypermethylation, disrupting apoptotic pathways and promoting tumor survival." (PMID 40881676, 2025). "Our study demonstrates that the functional restoration of death-associated protein kinase 1 (DAPK1), a novel tumor suppressor in HGSOC, induces potent tumor-specific cytotoxicity and inverts chemoresistance." (PMID 40563561, 2025). "Death-associated protein kinase 1 (DAPK1) is a well-known tumor suppressor gene involved in apoptosis, autophagy, and tumor progression." (PMID 40454931, 2025). "Aberrant expression of DAPK1 was shown in certain types of human cancer contributing to tumor progression and chemoresistance." (PMID 40563561, 2025). "Reduced cell viability, as measured by PARP cleavage in cell lines and increased Caspase 3/7 activity in cell lines and primary tumor cells, was observed upon the mammalian vector-based expression of DAPK1." (PMID 40563561, 2025). "Our study demonstrates that restoring the tumor suppressor DAPK1, frequently downregulated in HGSOC, effectively induces apoptosis and reverses chemoresistance." (PMID 40563561, 2025). "The chemokine IL-8 is known to enhance the infiltration of regulatory T-cells (Tregs) through the DAPK1/pyruvate kinase/lactate axis in response to fluctuations in tumor cell density." (PMID 40165895, 2025). "DAPK-1 is a tumor suppression gene and induces apoptosis in several cells associated in various diseases." (PMID 41189711, 2025). "By modulating these pathways, DAPK1 acts as a tumor suppressor inhibiting tumor growth and metastasis." (PMID 40563561, 2025). "Previous studies have shown that DAPK1 is a tumor-suppressive gene and is suppressed in various cancers." (PMID 40064799, 2025). "Although DAPK1 was initially identified as a significant tumor suppressor, the expanding network of its upstream and downstream pathways has potentially extended its roles to numerous diseases." (PMID 40918124, 2025). "DAPk forms a complex with PP2A to create a CIP2A–PP2A– unc-5 homolog B (UNC5H2)–DAPK1 protein complex that helps eliminate tumor cells." (PMID 41155727, 2025). "Targeting these downstream targets of DAPK-1 can alleviate stroke damage, obstruct the ability of Pin1 to activate oncogenic transcription factors, and suppress cell proliferation and tumor development." (PMID 40699815, 2025). "In our study, the OLP samples expressed DAPK-1 in a very intense manner, signifying that both its tumor-suppressing function and its pro-inflammatory role are present." (PMID 39553125, 2024). "Due to its pro-inflammatory nature and role as a tumor suppressor factor, DAPK-1 is highly expressed in OLP (both reticular and erosive types)." (PMID 39553125, 2024). "For tumor suppressors that can also act as resistance or insensitivity factors, such as DAPK1 or PTPN11, the nature of perturbation or knock-out will substantially bias their activity and function." (PMID 38724493, 2024). "In 1997, DAPK1 was cloned, and its tumor-suppressing ability was tested in two murine lung tumors through in vivo experiments that featured low expression levels of DAPK1 but the ability to metastasize." (PMID 39057063, 2024). "The dataset was then divided into two parts to investigate the relationship between DAPK1 expression and stemness, and a relatively high stemness index was observed in tumor tissue with low DAPK1 expression." (PMID 39057063, 2024).
tumor (continued). "DAPK1 is considered a significant tumor suppressor gene, capable of inhibiting tumor development by regulating apoptosis and the cell cycle." (PMID 39926603, 2024). "This motif of expression of DAPK-1 in the apparently normal epithelium adjacent to the tumor site is more prominent mainly in cases of moderately and well-differentiated carcinomas." (PMID 39553125, 2024). "To elaborate, DAPK1 controls tumor cell motility and invasion through autophagy, metastatic potential for anoikis, and escape from immune surveillance." (PMID 39057063, 2024). "This means that DAPK1 can act as an early tumor suppressor and also closely interact with CSCs and EMT regulators, which are prognostic markers of cancer metastasis." (PMID 39057063, 2024). "Some studies propose that aberrant expression of DAPK1 is correlated with the initiation and progression of various tumor types." (PMID 38463514, 2024). "In cancer progression, the mechanism by which DAPK1 inhibits tumor metastasis as a tumor suppressor involves various apoptotic signals in caspase-dependent apoptosis and caspase-independent autophagy." (PMID 39057063, 2024). "Considering that the low DAPK1 tumor group showed high levels and aggressiveness in tumor metastasis." (PMID 39057063, 2024). "Comprehensive mutation analysis illustrated gene mutations and their associations within the tumor microenvironment (TME), revealing differences in mutation load and copy number variation (CNV) between high and low DAPK1+ Macrophage risk score groups." (PMID 39926603, 2024). "Our results suggest that DAPK1 can not only act as a tumor suppressor when the prognosis of PTC cancer is poor, but it can also affect CSC formation." (PMID 39057063, 2024). "The IHC analysis of tissue microarrays showed that DAPK1 expression staining was located at both cytosol and nucleus of tumor cells." (PMID 38310291, 2024). "Initially, the downregulation or inactivation of DAPK1 can regulate the early stages of cancer proliferation as a tumor suppressor." (PMID 39057063, 2024). "DAPK (also termed DAPK1) a 16‐kDa tumor suppressor, constitutes one of the CaM‐regulated kinase superfamilies that relate to Ser/Thr kinases." (PMID 37901797, 2023). "The connection between cancer and DAPK-1 was confirmed when the DAPK-1 promoter regions were shown to be significantly methylated across different types of human tumours in comparison to their corresponding normal tissue samples." (PMID 37372454, 2023). "In this work, we analyzed the tumor microenvironment and found that the prognosis-related gene DAPK1 was correlated with several immune cells, immunostimulators and targeting drugs." (PMID 37065474, 2023). "Similar to DAPK-1, both DAPK-2 and DAPK-3 are regarded as tumour suppressors because they are both implicated in apoptotic cell death." (PMID 37372454, 2023). "DAPK1 is frequently down-regulated, which promotes tumor formation, metastasis, and resistance to chemotherapy." (PMID 37446908, 2023). "DAPK1 can enhance anti-tumor immunology, and DNA is hypermethylated in high WM_Score patients, whilst stromal-activation-related genes such as TGFB2 are hypomethylated." (PMID 37319315, 2023). "Spearman correlation analysis showed that DAPK1 was positively correlated with IL-8 expression and the expression of DAPK1 also fluctuated with tumor cell density." (PMID 36932390, 2023). "Here, specific immunostaining for uPAR clearly showed an increased uPAR expression in DAPK1 ko cells in the tumor center, as well as at the invasion front under CAM in vivo conditions." (PMID 35625969, 2022).
tumor (continued). "Tumor stage, pathology and DAPK1 were identified as independent prognostic factors by univariate Cox analysis." (PMID 36290392, 2022). "Increased tumor cell motility and de-adhesion (thus, promoting metastasis), as well as upregulated plasminogen-signaling, are shown when functionally analyzing the DAPK1 ko-related proteome." (PMID 35625969, 2022). "This mechanistic study strongly suggested a uPAR-mediated ECM remodeling at the tumor invasion front where we find remarkably reduced DAPK1 levels." (PMID 35625969, 2022). "DAPK1 is a serine/threonine kinase that acts as an important regulator of apoptosis and inhibits tumor cell growth and metastasis." (PMID 35935258, 2022). "In H&E stained histological images, we show that DAPK1 ko tumor cells formed loosely-packed tumor masses that disseminate into the CAM with intense tumor budding of single cells or small cell clusters." (PMID 35625969, 2022). "Analysis of DAPK1 in cancer has shown that it acts as a tumor suppressor gene, which participates in tumor development and metastatic activity by regulating autophagy and apoptosis." (PMID 35154442, 2022). "In contrast, the collagen patterns of DAPK1 ko cells resembled later stages of tumor invasion with more fibers along the invasion direction and reduced collagen density." (PMID 35625969, 2022). "Recent studies have found that DAPK1 is an important serine/threonine kinase and is involved in a variety of cell-to-cell interactions, such as apoptosis, autophagy, cellular blebbing, tumor metastasis, and inflammation." (PMID 35082934, 2022). "DAPK1 is emerging as a tumor suppressor for some cancers, including bladder, liver, colorectal and oesophageal squamous cell carcinomas." (PMID 36290392, 2022). "This invasive growth pattern is strongly reminiscent of the enhanced tumor budding observed by DAPK1 ko cells in vivo." (PMID 35625969, 2022). "To confirm that the enhanced tumor growth, as well as the increased ECM remodeling potential of HCT116 DAPK1 ko cells in CAM tissue, was caused by a DAPK1-dependent up-regulation of uPAR, we performed a 3D-tumor cell invasion assay in vitro." (PMID 35625969, 2022). "Our results indicate the high ECM remodeling potential of DAPK1 ko tumor cells at the tissue level and support our findings from proteomics." (PMID 35625969, 2022). "In the early stage of cancer, DAPK1 can suppress tumor growth and metastasis by increasing apoptosis." (PMID 34422899, 2021). "DAPK1 plays an important role in diverse apoptosis pathways, including tumor suppression and neuronal cell death." (PMID 33841091, 2021). "It has also been identified as a tumor suppressor, and several studies have shown that DAPK1 regulates cell adhesion, DNA repair, cell cycle checkpoint control, and nuclear receptors during cancer progression." (PMID 34831219, 2021). "The low DAPK1 tumor group consistently displayed more aggressive features, including more advanced TNM (tumor-node-metastasis) stage, and lower DFS." (PMID 34831219, 2021). "In order to investigate promoter methylation status in IDC tumor progression,DAPK1 gene promoter methylation was assessed in stages I, II/III andIV." (PMID 34455714, 2021). "DAPK1 is an important regulator of cell apoptotic pathways and DAPK1 promoter hypermethylation has previously been reported in ILBCs with a potential role in tumour progression." (PMID 33461604, 2021). "First, DAPK1 was identified as mediator of interferon-γ induced cell death and later the role as tumour suppressor became increasingly apparent." (PMID 32707646, 2020).